REN (renin)
Diseases named in the same sentence as REN in open-access papers (continued):
Sharing a sentence is not in itself a finding about the gene and the disease.
Hypertension (continued). "In summary, regarding to modulatory effects of crocin on Ang II-induced hypertension, it seems that the inhibitory effect of crocin on the cardiovascular system was partly mediated via suppression of renin-angiotensin system." (PMID 28884084, 2017). "The renin-angiotensin system plays a central role in blood pressure (BP) regulation, and its long-term activation contributes to hypertension." (PMID 28298457, 2017). "SBDD has led to the discovery of various drugs including neuraminidase and polymerase inhibitors for influenza, proteinase inhibitors for AIDS and hepatitis C virus, renin inhibitor for hypertension and anticancer agents." (PMID 28273150, 2017). "Renal efferent sympathetic activity participates in renin release, sodium retention, and reduced renal blood flow, which contribute to the development of hypertension." (PMID 28270938, 2017). "The renin-angiotensin-aldosterone system (RAAS) plays an important role in regulating hypertension by controlling vasoconstriction and intravascular fluid volume." (PMID 29207547, 2017). "Aliskiren is the only direct renin inhibitor that is clinically used as an oral drug to actively attenuate hypertension." (PMID 29184499, 2017). "ENPEP plays a role in the catabolic pathway of the renin-angiotensin system and is a major contributor to the development of clinical arterial hypertension in the body." (PMID 29900035, 2017). "Diabetes and hypertension are associated with an elevated risk of kidney failure while elevated HDL levels and renin-angiotensin blockade appear protective." (PMID 28666418, 2017). "The role of the renin–angiotensin system (RAS) in the pathogenesis of hypertension and other cardiovascular diseases is widely acknowledged." (PMID 28423630, 2017). "Angiotensin-Converting Enzyme 2 (ACE2) is a key enzyme in the renin-angiotensin system (RAS), which is implicated in the pathogenesis of hypertension and other cardiovascular diseases." (PMID 28423630, 2017). "Aliskiren (ALI) is the first non-peptide, orally active, highly potent, and selective inhibitor of human renin approved for use in the treatment of hypertension." (PMID 28598381, 2017). "Brain APA is believed to modulate the renin-Ang system and to be a therapeutic target in hypertension and cardiac dysfunction." (PMID 28421141, 2017). "Others have revealed evidence that both PM2.5 and high fructose diets induce hypertension through the renin-angiotensin system." (PMID 28545487, 2017). "Activation of renin-angiotensin-aldosterone system (RAAS) plays crucial role in pathogenesis of essential hypertension, hypertension related with kidney diseases and congestive heart failure (CHF)." (PMID 28710615, 2017). "Although patients with essential hypertension can present low renin levels, plasma renin activity (PRA) increases above 2 ng/mL/h after furosemide injection." (PMID 28699986, 2017). "A direct renin inhibitor, aliskiren, has been extensively applied in rats with spontaneous hypertension and can block Ang II production." (PMID 28700686, 2017). "Aliskiren, a novel direct renin inhibitor, has been clinically shown to reduce blood pressure in spontaneously hypertensive rats, patients with essential hypertension, and patients with type 2 diabetes." (PMID 28700686, 2017). "Its effect on hypertension is likely through the renin-angiotensinogen level, sympathetic nerve activity, endothelial function, hypertriglyceridemia, and glucose intolerance." (PMID 29367559, 2016). "They found that although hREN gene expression from the 140-kb transgene (Tg) as well as the endogenous mouse renin (mRen) gene was appropriately suppressed in their hypertension model animals, the 13-kb hREN Tg expression was inappropriately upregulated." (PMID 27861631, 2016). "Kidneys have been reported to have a significant role in blood pressure control via renin-angiotensin-aldosterone system and adenosine receptors are considered to be involved in kidney pathophysiology in the development of hypertension." (PMID 26907173, 2016).
Hypertension (continued). "About 25%-33% of EH patients exhibit low renin levels; accordingly, the majority of hypertensive patients in China suffer from low-renin hypertension (LRH), a well-known subtype of EH." (PMID 27391973, 2016). "This study presents an E. coli-based system for the rapid production of milligram quantities of a human renin substrate, which will be useful for both fundamental and clinical studies on renin and hypertension." (PMID 27052373, 2016). "GRA is a low renin hypertension characterized by high aldosterone/renin ratio, failure to suppress aldosterone with salt loading, and elevated 18-hydroxycortisol, 18-hydroxycorticosterone, and 18-oxocortisol levels." (PMID 27366333, 2016). "Excess aldosterone can cause the dysregulation of the renin-angiotensin-aldosterone system (RAAS) and lead to hypertension." (PMID 27781210, 2016). "Converting enzyme inhibitors (CEIs) are among the primary drugs that are used to treat arterial hypertension and reduce BP by interacting with the renin-angiotensin system of the kidneys." (PMID 26766419, 2016). "Both kidney and plasma levels of renin are low in the mRen2 rat making this a low-renin hypertension model." (PMID 27935823, 2016). "Studies using animal models have clearly demonstrated the involvement of the renin gene in the development of hypertension." (PMID 26753721, 2016). "Hypertension can activate the renin-angiotensin-aldosterone system (RAAS), and they influence each other." (PMID 27893867, 2016). "L-NAME induced hypertension is characterized by low circulating plasma renin and Ang-II levels and is attenuated by treatment with RAS blockers." (PMID 27467376, 2016). "Although the etiology of hypertension is complex, the renin-angiotensin system (RAS) plays a major role in the pathology of hypertension." (PMID 26857237, 2016). "In patients with CKD, hypertension likely occurs because of a combination of factors including sodium retention, increased renin–angiotensin system activity, and enhanced sympathetic nervous system activity." (PMID 27632175, 2016). "Sildenafil was shown to interfere in renin-angiotensin-aldosterone system (RAAS) during hypertension." (PMID 26858657, 2016). "Future studies utilizing the L-NAME model and other experimental hypertension models are needed to clarify the functional significance of CD renin in Ang-II independent hypertension." (PMID 27467376, 2016). "In contrast, compared to controls, CD specific renin knock out (KO) mice have similar blood pressure with varying Na intake but demonstrate attenuated hypertension in response to Ang-II infusion." (PMID 27467376, 2016). "Disordered uric acid was supposed to influence changes in renin and NOS1 in the pathogenesis of hypertension, and it was mentioned as a modifying and causal factor for human primary hypertension." (PMID 26907309, 2016). "The activation of the intrarenal renin–angiotensin–aldosterone system (RAAS) plays a major role in the pathogenesis of hypertension in ADPKD." (PMID 26753721, 2016). "A 46,XX girl presented with genital ambiguity and low renin hypertension; her 46,XY brother presented with precocious puberty." (PMID 27316665, 2016). "Renal failure reduces the afferent glomerular arteriolar pressure, leading to the activation of the renin-angiotensin system, leading to hypertension." (PMID 27703551, 2016). "Taken together, these findings illustrate the potential for adrenal‐produced renin and prorenin to contribute to the development and maintenance of hypertension." (PMID 26997629, 2016). "As UA can activate the renin-angiotensin system and is an independent predictor of hypertension incidence and progression in community-based cohorts, this suggests that over time hyperuricemia becomes superseded by hypertension as a main risk factor." (PMID 27978810, 2016). "One of the key mechanisms leading to the hypertension is an activated renin-angiotensin system and defective pressure natriuresis." (PMID 27079836, 2016).
Hypertension (continued). "IH is believed to contribute to the pathogenesis of hypertension in OSA through mechanisms that include activation of the renin-angiotensin system." (PMID 27977796, 2016). "The plasma renin concentration contributes significantly to cardiovascular and renal diseases like hypertension, coronary heart disease, and chronic kidney disease." (PMID 26969407, 2016). "Blockade of RAS with an angiotensin-converting enzyme inhibitor captopril, angiotensin receptor blocker losartan, or renin inhibitor aliskiren in young offspring from age 2 to 4 weeks of various animal models of hypertension counteracts programming effects." (PMID 27897982, 2016). "In general, inhibitors of the renin-angiotensin system (RAS) are a commonly used medicament in treatment of hypertension." (PMID 27872861, 2016). "In individuals with mild-to-moderate hypertension, a high renin–sodium profile before and after antihypertensive treatment was independently associated with a higher subsequent risk of myocardial infarction." (PMID 28066329, 2016). "A key remaining question pertains to the role of CD renin in other forms of Ang-II independent hypertension." (PMID 27467376, 2016). "Renin, which is closely related with hypertension, is the first rate-limiting enzyme of the RAS, and cAMP functions as a key effecter in this system." (PMID 27391973, 2016). "The inhibition of renin-angiotensin system in experimental animals and clinical studies has proven to be effective in lowering blood pressure in hypertension." (PMID 27348013, 2016). "An important role for the renin-angiotensin system (RAS) in promoting hypertension and related end-organ damage is well established." (PMID 27066371, 2016). "Newer experimental approaches to treating hypertension involve the use of endothelin antagonists (e.g., bosentan), renin antagonists (e.g., aliskiren), and surgical renal denervation." (PMID 27524972, 2016). "The objective of this study was to evaluate the antihypertensive effects of mineralocorticoid receptor antagonists (MRAs) as add-on therapy to renin–angiotensin system (RAS) inhibitor(s) in patients with hypertension and DM." (PMID 26674759, 2016). "Converting enzyme inhibitors (CEIs) are among the first drugs that are administered for arterial hypertension and prominently reduce BP primarily by interacting with the renin-angiotensin system of the kidneys." (PMID 26766419, 2016). "Similar results have been observed in diabetic mRen2 rats, which constitutively express murine renin cDNA; however, this model is confounded by the development of malignant-phase hypertension." (PMID 26814757, 2016). "The hypertensive patients with polycystic kidney disease showed significantly higher plasma renin activity than patients with only essential hypertension." (PMID 26753721, 2016). "The link between hyperparathyroidism and hypertensive disorders is proposed to be related to the interaction of PTH with the renin-aldosterone system, the sympathetic nervous system, and the vascular endothelium." (PMID 27340578, 2016). "All subjects had hypertension with elevated aldosterone levels despite low plasma renin activity (PRA)." (PMID 25907736, 2015). "Hypertension, along with increases in vascular shear stress, overactivation of the renin-angiotensin system and overproduction of inflammatory cytokines cooperates with hyperglycemia in the generation of oxidative stress and inflammation." (PMID 26177037, 2015). "This condition is usually diagnosed in adolescents and young adults and is typically characterized by sustained hypertension well responding to antihypertensive treatment targeting the renin-angiotensin-aldosterone (RAA) system." (PMID 26084817, 2015). "Combined use of statins, amlodipine, and renin-angiotensin-aldosterone systeminhibitors improves the antihypertensive response and endothelial function inpatients with hypertension and diabetes." (PMID 26465872, 2015).
Hypertension (continued). "Along with minerals, the renin-angiotensin-aldosterone system has an important function in hypertension, as its activation results in the conversion of angiotensin I to angiotensin II, being the latter a potent vasoconstrictor." (PMID 26569268, 2015). "Aspartic proteases are a class of enzymes that play a causative role in numerous diseases such as malaria (plasmepsins), Alzheimer’s disease (β-secretase), fungal infections (secreted aspartic proteases), and hypertension (renin)." (PMID 26287174, 2015). "More than 70 % of hypertensive patients have renin related mechanisms as the aetiology of their hypertension." (PMID 26486596, 2015). "The Gata5-null mice exhibit several essential features of low-renin hypertension: significant increase in BP, low-renin plasma activity, salt sensitivity and severe renal alterations." (PMID 26617239, 2015). "Hypertension‐induced structural remodeling of the left atrium (LA) has been suggested to involve the renin–angiotensin system." (PMID 25626873, 2015). "Hyperuricemia was found to increase the synthesis of nitric oxide, increasing the release of inflammatory mediators and renin angiotensin levels and resulting in endothelial dysfunction, atherosclerosis, and hypertension." (PMID 26464873, 2015). "The renin–angiotensin–aldosterone system is the main hormonal regulator of BP and its activation leads to hypertension." (PMID 26617239, 2015). "Synthetic ACE inhibitors (captopril, enalapril, lisinopril, etc.), renin inhibitor (aliskiren), and angiotensin receptor blockers are traditionally used to treat congestive heart failure and hypertension." (PMID 26715103, 2015). "Circulating and local renin-angiotensin system (RAS) components are strictly associated with cardiovascular complications, especially in the development and progression of hypertension." (PMID 26388783, 2015). "Present studies showed that the disorders of hypothalamus-pituitary-adrenal cortex (HPA) axis, sympathetic nerve-adrenal medulla (SAM) system, and renin-angiotensin-aldosterone system (RAS) would lead to stress-induced hypertension." (PMID 26229544, 2015). "Renin inhibitors are new while thiazide diuretics are first-class drugs used for treatment of hypertension." (PMID 26465969, 2015). "This elevation results in hypertension (via disturbances in the renin-angiotensin-aldosterone system), cardiac hypertrophy, and myocardial dysfunction." (PMID 33530149, 2015). "Following the discovery of renin as a pressor molecule, the renin-angiotensin system (RAS) has been established as one of the major pathways involved in both the development of hypertension and in fluid homeostasis." (PMID 25971747, 2015). "Increased renin synthesis leads to an elevated angiotensin II production, which is a strong vasoconstrictor, enabling the development of hypertension and left ventricular hypertrophy." (PMID 26000280, 2015). "Among the 55 hypertensive patients, changes in diastolic blood pressure (DBP) were significantly different according to the genetic variant of renin C-5312T in response to telmisartan and valsartan therapy." (PMID 26495141, 2015). "Diabetic retinopathy features inflammation as well as injury to glial cells and the microvasculature, which are influenced by hypertension and overactivity of the renin-angiotensin system." (PMID 26222724, 2015). "Previous studies have examined the importance of the systemic renin-angiotensin system in the programming of hypertension." (PMID 26719973, 2015). "Sympathetic activation and renin-angiotensin system are essential for development and sustenance of hypertension." (PMID 26486596, 2015). "Data from the literature indicate that hypertension leads to the kidneys damage through activation of the renin–angiotensin system (RAS)." (PMID 24578186, 2015).
Hypertension (continued). "Nowadays, it is well accepted that perinatal protein malnutrition raise risks of hypertension by mechanisms that include reduced nephron morphology and function, and dysfunction on the renin-angiotensin system." (PMID 26635631, 2015). "In RenTgMK mice the hepatic secretion of active renin elevates renin enzymatic activity and circulating Ang II levels independently of the body’s homeostatic control mechanisms, and these mice thus develop severe hypertension." (PMID 26494430, 2015). "In short, hypertension was developed by UA-mediated renal vasoconstriction resulting from a reduction in endothelial levels of nitric oxide, with activation of renin-angiotensin system." (PMID 26893924, 2015). "The renin-angiotensin aldosterone system (RAAS) plays a pivotal role in the development of hypertension." (PMID 25815211, 2015). "Renal medullary PRR mediates angiotensin II-induced hypertension, likely by amplifying the local renin response." (PMID 26554902, 2015). "We next assessed the possible role of renin-angiotensin system activation in the hypertension shown by Alk1+/− mice." (PMID 26398936, 2015). "The human renin gene has been widely known to be involved in essential hypertension (EH) pathogenesis." (PMID 26090220, 2015). "Vitamin D3 supplementation reduces blood pressure in patients with essential hypertension and reduces also plasma renin activity and angiotensin II levels in hyperparathyroidism patients." (PMID 26000280, 2015). "Several studies have established that the renin-angiotensin system, including the ACE insertion/deletion genetic polymorphisms has been implicated in the pathogenesis of essential hypertension." (PMID 25973747, 2015). "Uric acid and renin levels were found to be higher in adolescents aged 13–18 years with essential hypertension than in an age- and gender-matched normotensive control group." (PMID 26464873, 2015). "The plasmatic renin activity was increased five weeks after pinealectomy, possibly reflecting an increased sympathetic tone, a major contributor to hypertension development in pinealectomized animals." (PMID 25110398, 2014). "It is well documented that angiotensin II (Ang II), the main effector peptide of the renin-angiotensin system, produces hypertension, oxidative stress, vascular hypertrophy, and endothelial dysfunction." (PMID 25400581, 2014). "Aliskiren, a direct renin inhibitor recently introduced (Novartis) as an anti-hypertension drug, was shown to also reverse remodeling in a coronary ligation-induced MI model independently of its effect on blood pressure." (PMID 24667808, 2014). "Elevated blood levels of renin and aldosterone confirm the clinical suspicion of renin-mediated hypertension." (PMID 25177679, 2014). "Aliskiren, a direct renin inhibitor newly developed, produced a marked therapeutic effect on hypertension and hypertrophy." (PMID 24702827, 2014). "The symptoms of the patient were consistent with the renin-secreting tumor triad, which comprises hypertension, hypokalemia and elevated PRA." (PMID 25289084, 2014). "The beneficial effects on hypertension (blood pressure lowering, either systolic or diastolic) due to decreased activity of both the sympathetic nervous system and the renin-angiotensin system was also documented." (PMID 27437465, 2014). "We used double transgenic rats harboring both human renin and angiotensinogen genes (dTGR) that develop severe hypertension, target-organ damage, and die untreated within 7–8 weeks." (PMID 24710077, 2014). "The renin-secreting tumor triad consists of hypertension, hypokalemia and elevated plasma renin activity (PRA)." (PMID 25289084, 2014). "Patients typically present with a long history of headaches leading to a diagnosis of severe hypertension that responds well to antihypertensive treatment targeting the renin-angiotensin-aldosterone system." (PMID 25177679, 2014).